CCDC9 (coiled-coil domain containing 9)
Description:
Probable component of the exon junction complex (EJC), a multiprotein complex that associates immediately upstream of the exon-exon junction on mRNAs and serves as a positional landmark for the intron exon structure of genes and directs post-transcriptional processes in the cytoplasm such as mRNA export, nonsense-mediated mRNA decay (NMD) or translation.
Synonyms: DKFZP586M1019
Tractability: PROTAC: ubiquitination databases record sites on it; its protein half-life has been measured.
Gene: Protein-coding gene on chromosome 19 (47,255,980 to 47,274,055, forward strand). Ensembl gene ENSG00000105321.
Subcellular location (Human Protein Atlas): Cytosol
Gene Ontology:
Molecular function: protein binding; RNA binding
Cellular component: exon-exon junction complex
Genetic constraint (gnomAD): Loss-of-function variants: 52 observed, 58.53 expected, observed/expected ratio (o/e) 0.89, 90% interval 0.71 to 1.12. The synonymous counts are far from expectation, so gnomAD's model fits this gene poorly and the ratio says little. Missense variants: 834 observed, 715.36 expected, observed/expected ratio (o/e) 1.17, 90% interval 1.1 to 1.23. Synonymous variants: 332 observed, 255.87 expected, observed/expected ratio (o/e) 1.3, 90% interval 1.18 to 1.42.
Homologues: Orthologues: chimpanzee CCDC9 (98% identical), macaque CCDC9 (95% identical), dog CCDC9 (85% identical), pig CCDC9 (84% identical), mouse Ccdc9 (78% identical), rat Ccdc9 (73% identical), rabbit CCDC9 (66% identical), zebrafish ccdc9 (48% identical), tropical clawed frog ccdc9 (47% identical), Caenorhabditis elegans C10G8.8 (15% identical). Paralogues in human: CCDC9B (20% identical).
Diseases named in the same sentence as CCDC9 in open-access papers:
CCDC9 is named in the same sentence as 6 diseases in open-access papers, as found by Europe PMC text mining. Sharing a sentence is not in itself a finding about the gene and the disease. The quoted sentences say what the papers report.
asthenozoospermia (2 papers, 2023 to 2024). "CCDC9 was also previously identified as a novel candidate gene of severe asthenozoospermia and has been reported to regulate sperm motility and spermiogenesis." (PMID 38705876, 2024). "Mutations in CCDC9 and CCDC151 are detected in patients with severe asthenozoospermia." (PMID 37601242, 2023).
male infertility (1 paper, 2023). The inability of the male to effect fertilization of an ovum after a specified period of unprotected intercourse. "Knockout of Ccdc9, Ccdc38, Ccdc42, Ccdc62, Ccdc87 and Ccdc136 results in male infertility in mouse models because of defects in sperm flagella." (PMID 37601242, 2023).
CCDC9 also shares sentences with these, for which no sentence is quoted: cancer (1 paper); ovarian carcinoma (1); Stroke (1); tumor (1).